AARS1 (alanyl-tRNA synthetase 1)
Description:
Catalyzes the attachment of alanine to tRNA(Ala) in a two-step reaction: alanine is first activated by ATP to form Ala-AMP and then transferred to the acceptor end of tRNA(Ala). Also edits incorrectly charged tRNA(Ala) via its editing domain. Protein lactylation takes place in a two-step reaction: lactate is first activated by ATP to form lactate-AMP and then transferred to lysine residues of target proteins. Acts as a positive regulator of the Hippo pathway by mediating lactylation of TEAD1 and YAP1.
Synonyms: AlaRS; AARS; CMT2N; DEE29; EIEE29; HDLS2; TTD8
Tractability: Small molecule: a structure with a bound ligand is known. PROTAC: UniProt records ubiquitination sites on it; ubiquitination databases record sites on it.
Target class: Enzyme; Ligase
Gene: Protein-coding gene on chromosome 16 (70,251,983 to 70,289,707, reverse strand). Ensembl gene ENSG00000090861.
Subcellular location: Cytoplasm; Nucleus
Subcellular location (Human Protein Atlas): Cytosol
Pathways (Reactome):
Metabolism of proteins: Cytosolic tRNA aminoacylation
Gene Ontology:
Molecular function: alanine-tRNA ligase activity; aminoacyl-tRNA deacylase activity; peptide lactyltransferase (ATP-dependent) activity; Ser-tRNA(Ala) deacylase activity; tRNA binding; amino acid binding; aminoacyl-tRNA ligase activity; ATP binding; nucleic acid binding; nucleotide binding; zinc ion binding
Biological process: alanyl-tRNA aminoacylation; positive regulation of hippo signaling; tRNA aminoacylation for protein translation; tRNA modification; tRNA processing; aminoacyl-tRNA metabolism involved in translational fidelity; regulation of cytoplasmic translational fidelity; tRNA aminoacylation
Cellular component: cytoplasm; cytosol; extracellular exosome; membrane; nucleus
Genetic constraint (gnomAD): Loss-of-function variants: 69 observed, 109.23 expected, observed/expected ratio (o/e) 0.63, 90% interval 0.52 to 0.77. The upper end of that interval is the gene's LOEUF score, 0.77, which puts it in group 3 of 6, group 1 being the genes least tolerant of losing a copy. Missense variants: 1,185 observed, 1,287.7 expected, observed/expected ratio (o/e) 0.92, 90% interval 0.88 to 0.96. Synonymous variants: 489 observed, 488.83 expected, observed/expected ratio (o/e) 1, 90% interval 0.93 to 1.08.
Gene-disease validity (ClinGen):
ClinGen rates the evidence that AARS1 causes each of these diseases.
Charcot-Marie-Tooth disease axonal type 2N (autosomal dominant): Definitive.
developmental and epileptic encephalopathy, 29 (autosomal recessive): Definitive. Any early infantile epileptic encephalopathy in which the cause of the disease is a mutation in the AARS gene.
AARS1-related leukoencephalopathy (autosomal dominant): Limited. Any leukoencephalopathy in which the cause of the disease is a variant in the AARS1 gene.
Homologues: Orthologues: chimpanzee AARS1 (99% identical), macaque AARS1 (99% identical), guinea pig AARS1 (96% identical), dog AARS1 (96% identical), pig AARS1 (96% identical), mouse Aars1 (96% identical), rabbit AARS1 (95% identical), rat Aars1 (95% identical), tropical clawed frog aars1 (83% identical), zebrafish aars1 (82% identical), Drosophila melanogaster AlaRS (61% identical), Caenorhabditis elegans aars-2 (58% identical). Paralogues in human: AARS2 (45% identical), AARSD1 (10% identical).
Diseases named in the same sentence as AARS1 in open-access papers:
AARS1 is named in the same sentence as 82 diseases in open-access papers, as found by Europe PMC text mining. Sharing a sentence is not in itself a finding about the gene and the disease. The quoted sentences say what the papers report.
gastric cancer (12 papers, 2024 to 2026). A primary or metastatic malignant neoplasm involving the stomach. "This lactylation is mediated by AARS1, which is elevated in gastric cancer and is associated with poor prognosis." (PMID 40128358, 2025). "Meanwhile, R77Q mutation in AARS1 has been detected evidently in gastric cancer and, in fact, promotes the enzymatic capacity of AARS1." (PMID 41008630, 2025). "Interestingly, an R77Q mutation frequently found in patients with gastric cancer enhances the catalytic capacity of AARS1, while mutating other essential lactate-binding residues to alanine simultaneously eliminates AARSs’ binding to lactate." (PMID 41008630, 2025). "In contrast, another study has shown that AARS1 and AARS2 regulate Kla on METTL16, which causes copper-induced gastric cancer cell death." (PMID 40128358, 2025). "AARS1 and YAP-TEAD1 constitute a positive feedback loop in which AARS1 catalyzes YAP-TEAD1 lactylation while YAP-TEAD1 upregulates AARS1 expression, leading to gastric cancer cell proliferation and apoptosis suppression." (PMID 40994548, 2025). "Another study found that AARS1 lactylates the YAP/TEAD1 complex in gastric cancer (GC) cells using the same catalytic mechanism." (PMID 41373440, 2025). "The balance between AARS1/AARS2’s lactylation and alanine transfer functions involves competitive inhibition: alanine inhibits AARS’s lactylation activity, with β-alanine pretreatment dramatically reducing the lactylation levels in gastric cancer cells." (PMID 40994548, 2025). "Consistently, we found AARS1 to be upregulated and associated with YAP-TEAD1 lactylation in gastric cancer (GC), and found that elevated expression of AARS1 was strongly associated with TNM stages and poor clinical outcomes." (PMID 38512451, 2024). "In gastric cancer, increased copper level improves AARS1/AARS2-METTL16 interaction." (PMID 40994548, 2025). "AARS1 expression is positively correlated with a large tumor size, lymph node metastasis, and a high tumor stage in gastric cancer, suggesting that AARS1 may promote tumor progression." (PMID 41008630, 2025). "In gastric cancer, AARS1 lactylates YAP, which accelerates cancer cell proliferation." (PMID 40128358, 2025). "AARS1 is significantly overexpressed in gastric cancer (GC), duodenal cancer (DC), and many other types of cancer, and it is negatively associated with the survival of gastric cancer and breast cancer patients." (PMID 41008630, 2025). "In gastric cancer cells, elevated copper levels promote lactylation of METTL16 at the K229 site, mediated by enhanced interaction with acetyltransferases alanyl-tRNA synthetase 1/2 (AARS1/AARS2)." (PMID 41459114, 2026). "The overexpression of AARS1 enhanced cell proliferation and invasion, whereas AARS1 knockdown suppressed these capacities in both Hutu80 and WDC-1 gastric cancer cell lines." (PMID 41008630, 2025). "AARS1 could catalyse YAP‐K90la and TEAD1‐K108la, core components of the Hippo pathway, enhancing their interaction and ultimately exacerbating the malignancy of gastric cancer." (PMID 40984037, 2025). "Specifically, AARS1 was found to sense intracellular lactate and translocate into the nucleus to lactylate and activate the YAP-TEAD complex; and AARS1 itself was identified as a Hippo target gene that forms a positive-feedback loop with YAP-TEAD to promote gastric cancer (GC) cell proliferation." (PMID 38512451, 2024). "The authors hypothesized that AARS1, as a Hippo target gene, can form a positive feedback loop with YAP-TEAD, promoting gastric cancer cell proliferation, whereas AARS1 expression is correlated with poor prognosis in GC patients." (PMID 39516356, 2024).
Leukoencephalopathy (6 papers, 2018 to 2024). This term describes abnormality of the white matter of the cerebrum resulting from damage to the myelin sheaths of nerve cells. "Leukoencephalopathy linked to AARS1 mutations is characterized on MRI by progressive posterior predominant leukoencephalopathy evolving to include the frontal white matter." (PMID 35683020, 2022). "Interestingly, a damaging monoallelic variant in the AARS1 gene has also been found to cause leukoencephalopathy in two members of an affected Swedish family." (PMID 36330207, 2022). "A third, still poorly defined group of POLD-like leukoencephalopathies with or without epilepsy, is linked to mutations in AARS1." (PMID 35683020, 2022). "No neuropathological studies are available in cases with leukoencephalopathy linked to AARS1 mutations." (PMID 35683020, 2022). "The rare group of leukoencephalopathies linked to mutations in AARS1 are not microgliopathies." (PMID 35683020, 2022). "The five main classifications of leukoencephalopathies are CSF1R-related leukoencephalopathy, AARS2-related leukoencephalopathy, AARS1-related leukoencephalopathy, HDLS-S-related leukoencephalopathy and CSF1R/AARS1/AARS2-negative ALSP." (PMID 35185751, 2021).
neuropathy (6 papers, 2014 to 2025). A disorder affecting the nervous system that manifests with pain, tingling, numbness, and/or muscle weakness. "Previously, we demonstrated that neuropathy-associated AARS1 alleles have dominant-negative properties in a humanized yeast assay." (PMID 40491354, 2025). "Neuropathy-causing AARS1 mutations have been identified in each of the AlaRS domains." (PMID 37274211, 2023). "AARS1 variants that cause neuropathy do not affect proofreading in vitro, including mutations located within the AlaRS editing domain." (PMID 37274211, 2023). "Proteomic data from four affected individuals suggest that mitochondrial dysfunction and inflammation could be involved in AARS1 neuropathy." (PMID 35971119, 2022). "Thus, we speculate that the observed mitochondrial involvement in monoallelic AARS1 neuropathy could potentially be a secondary effect or alternatively, that altered synthesis of mitochondrial proteins in the cytosol could affect mitochondrial function in patients with AARS1 neuropathy." (PMID 35971119, 2022). "Alanyl-tRNA synthetase 1 (AARS1) has been implicated in multi-system recessive phenotypes and in later-onset dominant neuropathy; to date, no single variant has been associated with both dominant and recessive diseases, raising questions about shared mechanisms between the two inheritance patterns." (PMID 40491354, 2025).
breast cancer (4 papers, 2020 to 2025). A primary or metastatic malignant neoplasm involving the breast.
leukodystrophies (4 papers, 2021 to 2023). "In the case of leukodystrophies caused by bi-allelic mutations in genes encoding aaRS1, caused by hypomorphic mutations, further studies are required to determine if there is an underlying mechanism that involves translation deregulation and/or shares features with POLR3-HLD." (PMID 34395528, 2021).
axonal neuropathies (3 papers, 2015 to 2025). "Another AARS1 variant was found to cause a mild myelopathy in addition to axonal neuropathy, further expanding the disease spectrum associated with dominant AARS1 mutations." (PMID 37274211, 2023). "Variants in AARS1 have been associated with multi-system recessive phenotypes and with dominant axonal peripheral neuropathy; however, no single variant has been reported to cause both dominant and recessive disease." (PMID 40491354, 2025).
Charcot-Marie-Tooth disease (3 papers, 2023). An inherited degenerative disorder involving the peripheral nerves. "The most common condition, the Charcot-Marie-Tooth disease (CMT), is associated with dominant, monoallelic mutations in six aaRSs genes (e.g.,YARS1, MARS1, KARS1, WARS1, AARS1, GARS1, and HARS1)." (PMID 37495112, 2023). "Thus far, autosomal dominant mutations in AARS1, GARS1, HARS1, MARS1, WARS1, SARS1 and YARS1 have been linked to peripheral neuropathies, predominantly Charcot-Marie-Tooth (CMT) disease." (PMID 37274211, 2023).
Epileptic encephalopathy (3 papers, 2019 to 2024). A condition in which epileptiform abnormalities are believed to contribute to the progressive disturbance in cerebral function. "Mutations in alanyl-tRNA synthetase 1 (AARS1) may show two distinct phenotypes with neurological symptoms: (i): epileptic encephalopathy with deficient myelination (DEE29; OMIM# 616239); and (ii): progressive posterior predominant leukoencephalopathy." (PMID 35683020, 2022).
bladder cancer (2 papers, 2025). "In HT1376 and RT112 cells (human bladder cancer cells), the inhibition of AARS1 suppressed the lactylation of YTH N6-methyladenosine RNA-binding protein C1 (YTHDC1) and promoted the protein levels of YTHDC1." (PMID 41008630, 2025). "Consistently, an in vitro investigation revealed that AARS1 expression was increased in E-resistant bladder cancer cells and further upregulated in response to EPI treatment." (PMID 40634292, 2025). "Meanwhile, in bladder cancer, AARS1-mediated lactylation promotes RNF183-mediated ubiquitination and the degradation of YTHDC1." (PMID 41008630, 2025).
colon adenocarcinoma (2 papers, 2020 to 2025). "A combination survival analysis revealed that patients with a high co-expression of ULBP1, AARS1, and DDIT3 exhibited a 2.2-fold increased risk of death from colon adenocarcinoma (COAD) compared to patients with a low expression of all three genes." (PMID 41008630, 2025).
acute liver failure (1 paper, 2024). Rapid deterioration of liver function causing encephalopathy and coagulopathy. "However, as AARS1 plays a fundamental role in tRNA aminoacylation and protein synthesis and its deficiency has been reported to be associated with neurological disorders and acute liver failure, therapeutic targeting of AARS1 to treat GC warrants further investigations." (PMID 38512451, 2024).
acute lung injury (1 paper, 2025). A condition of lung damage that is characterized by bilateral pulmonary infiltrates (pulmonary edema) rich in neutrophils, and in the absence of clinical heart failure. "In sepsis-induced acute lung injury (SI-ALI), PDK4 hyperactivation drives excessive lactate production in epithelial cells, triggering AARS1/HDAC9-mediated LPCAT2 lactylation." (PMID 41057687, 2025).
cerebellar degeneration (1 paper, 2023). Degeneration of the cerebellum. "Specifically, mutations in AARS1 have been identified as the likely cause of Swedish-type hereditary diffuse leukoencephalopathy with spheroids 2 (HDLS2 or HDLS-S), and a dominant HARS1 variant has been linked to cerebellar degeneration, cognitive impairments, and peripheral neuropathy." (PMID 37274211, 2023).
diabetic nephropathy (1 paper, 2025). "The present study showed that AARS1 induced the lactylation of H3K18 and STAT1 to regulate ELOVL5 transcription, thus triggering ferroptosis in a diabetic nephropathy model." (PMID 40987895, 2025).
duodenal cancer (1 paper, 2025). "In addition, the expression of AARS1 increasingly enhanced during duodenal cancer progression." (PMID 41008630, 2025).
esophageal squamous cell carcinoma (1 paper, 2025). Esophageal squamous cell carcinoma (ESCC) is a type of esophageal carcinoma (EC) that can affect any part of the esophagus, but is usually located in the upper or middle third. "Additionally, AARS1 was identified as the primary lactyltransferase responsible for catalyzing the lactylation of nudix hydrolase 21 (NUDT21) in esophageal squamous cell carcinoma (ESCC) cell lines (KYSE30 cells)." (PMID 41008630, 2025).
HCMV infection (1 paper, 2025). "However, our lactylome datasets demonstrate that AARS1 contributes to the widespread IDR lactylation that we uncover during HCMV infection, a feature that may be conserved more broadly across kingdoms of life, yet it remains unclear why this preference exists." (PMID 39772686, 2025).
liver cancer (1 paper, 2025). An epithelial or non-epithelial malignant neoplasm that arises from the liver. "Moreover, mutation at position 312 of ASH2L significantly diminished the ability of AARS1 to enhance VEGFA expression in HCC cells, indicating that AARS1 promoted angiogenesis in liver cancer through ASH2L lactylation." (PMID 40726441, 2025).
lymph node metastasis (1 paper, 2024). "In addition, expression levels of AARS1 were found to be positively correlated with Helicobacter pylori infection, tumor size, and tumor stages (weakly with lymph node metastasis)." (PMID 38512451, 2024).